CD4 (CD4 molecule)
Diseases named in the same sentence as CD4 in open-access papers (continued):
Sharing a sentence is not in itself a finding about the gene and the disease.
helminth infection (141 papers, 2006 to 2025). "Increase in the number of CD8+ cells and a decrease in the number of CD4+ cells, have been observed in individuals with general immune activation caused by persistent helminthic infection." (PMID 39609767, 2024). "T cell activation and proliferation contribute to productive HIV infection of memory CD4 T cells and helminth infections have been associated with systemic T cell activation." (PMID 37644394, 2023). "Recently, it has been reported that transcription factor NLRP3 in CD4+ T cells acts as a key transcription factor in Th2 immune response, which is associated with protective immunity to helminth infection." (PMID 32976511, 2020). "CD4+ T cells are requisite for immunity against helminth infections in both mice and humans, but the mechanisms underlying their activation, function, and maintenance during these infections are not well understood." (PMID 31072011, 2019). "Helminth infections are usually associated with Th2-type immune response characterized by the activation of CD4+ T helper cells and secretion of IL-4, IL-5, IL-9 and IL-13." (PMID 30189894, 2018). "By contrast, helminth infections induce IL-4/IL-5 and IL-13 producing CD4 T cells and regulatory T cells associated with the alternative activation of macrophages for repair of tissues injured upon migration of worms across different body compartments." (PMID 28759590, 2017). "The results presented herein point to a high prevalence of helminth infection in this vulnerable population, and that hookworm infection is associated with sub-optimal health outcomes, i.e. lower CD4." (PMID 28542260, 2017). "Helminth infections in human host cause an immune response associated with elevated levels of IgE, tissue eosinophilia and mastocytosis, and with the presence of CD4+ T cells that preferentially produce IL-4, IL-5, and IL-13." (PMID 27980457, 2016). "Statistically significant association was found between CD4 count of less than 200 cells/μL and helminth infection (p = 0.05)." (PMID 26842519, 2015). "None of these studies documented CTX-P as a potential confounder or causal factor for the altered prevalence of helminth infection in patients with lower CD4 counts." (PMID 25993501, 2015). "We have previously shown that helminths infections cause immune activation by increasing memory CD4+ T cells which are reported to largely express CCR5 by the non-syncytium inducing HIV-1C subtype in Ethiopia." (PMID 26187732, 2015). "Our data on the role of IL-10 and TGFβ in the helminth infection associated modulation of CD4+ Th1 responses implicate IL-10 as the major player in the down modulation of Th1 responses in active TB, at least in the context of filarial infections." (PMID 25211342, 2014). "Experimental evidence points to the possible involvement of regulatory T cells in other chronic helminth infections, such as those caused by hookworm, where there is an increased number of circulating CD4+CD25+Foxp3+ T cells, compared to healthy individuals." (PMID 24348679, 2013). "In the present study the risk of helminth infection was higher in females with a reduced CD4 cell count, and in subjects with a detectable viral load." (PMID 23967365, 2013). "This is in agreement with previous studies conducted in pregnant females in Uganda and Rwanda where CD4 counts correlated negatively with the risk of helminth infection." (PMID 23967365, 2013). "We previously found that IL-22 producing CD4+ cells were associated with helminth infection and disease remission in a patient with ulcerative colitis." (PMID 22829946, 2012). "As with most helminth infections, schistosomiasis is associated with the development of a CD4+ Th2 cell response." (PMID 19360123, 2009). "Association of helminth infections with percent of HLA-DRpos CD4 T cells." (PMID 31425508, 2019).
helminth infection (continued). "It is likely that the underlying helminth infection and possibly genetic and other unknown environmental factors may have caused the induction of mixed Th1/Th2 Mtb-specific CD4 T cell responses in patients from TZ." (PMID 28759590, 2017). "Also, helminth infections were associated with lower levels of hemoglobin and CD4 counts in HIV-positive mothers." (PMID 24575099, 2014). "Baseline CD4 count was correlated with risk of helminth infection in this cohort." (PMID 20361031, 2010). "After CD4 count was controlled for, rural residence (RR 1.40, 95% CI: 1.08–1.81), having no education (RR 1.57, 95% CI: 1.07–2.30), and higher CD4 count (RR 1.36, 95% CI: 1.07–1.73) remained independently associated with risk of helminth infection." (PMID 20361031, 2010). "However, low CD4 count (< 200 cells/μL) was associated with intestinal helminthic infection." (PMID 26842519, 2015). "One study tracked CX3CR1+CD4+ T cells in helminth infection models, identifying them as an activated, tissue-homing population with diverse cytokine production capacities." (PMID 40634636, 2025). "But unlike the elevated numbers of Foxp3‐expressing regulatory T cells reported with helminth infections, we observed fewer CD4+/Foxp3+ Treg cells in the colons of mice with FMT-P." (PMID 39466773, 2024). "Regardless, a concept supported by our findings is that, as a whole, natural or therapeutic helminth infections can be important elements in the prevention and amelioration of aberrant or excessive CD4 T-cell-mediated disease." (PMID 39439825, 2024). "With regard to the different CD4+ cell populations, the role of helminth infections was previously discussed, Th2 being the leading pathway for the immune defense against helminths and other protozoa." (PMID 37997984, 2023). "Most of these signaling substances emanate from CD4+ T cells, which play a key role in the establishment of the cytokine environment and are essential for the immune response during helminth infections." (PMID 37887717, 2023). "In this study, the main finding in the context of intracellular cytokine production of CD4+ T cells is that helminth infection reduced the frequency of IFN-γ+ T cells in a helminth species dependent pattern." (PMID 36662839, 2023). "injection of an anti-CD4 antibody on the same day as helminth infection (day 0) and again on day 4 after infection." (PMID 37018382, 2023). "In LTBI positive individuals combined helminth infection reduced IFN-γ+CD4+ cells in PBMCs stimulated with PPD and SEB." (PMID 36662839, 2023). "RELMβ promotes secretion of Muc2, regulates macrophage and CD4+ T cell responses in response to helminth infection, and promotes CD4+ T cell recruitment and mediation of IEC hyperplasia during pathogenic intestinal bacterial infection." (PMID 36000805, 2022). "The accumulation of basophils in the lymph nodes after helminth infection depends on IL-3 from CD4+ T cells, while IL-3 supplied by skin-resident CD4+ memory T cells is essential for their recruitment to the skin in the setting of tick bite." (PMID 36618424, 2022). "In recent years, some studies have confirmed that CD4+ T cells are involved in controlling parasite load, and their absence leads to significant mortality in helminth infections." (PMID 36046744, 2022). "Patients with helminth infection had a higher frequency of CD4 + Fox P3 + T cells (Tregs) and a lower frequency of CD4 + IFN-γ + T cells, but these effects were reversed after treatment." (PMID 36359526, 2022). "As expected in a helminth infection, the frequency and number of IL-4+ CD4+ Th2 cells increased in both the MLN and small intestine upon H. polygyrus infection." (PMID 35428872, 2022). "For example, primary infection activates memory CD4+ T cells and alternatively activated macrophages that mediate resistance against secondary helminth infection." (PMID 35572520, 2022).
helminth infection (continued). "In mice where ILC2 are genetically ablated, IL-5 production by CD4+ T cells drops in MLN during helminth infection resulting in ablated expulsion of worm." (PMID 35145516, 2022). "As such, CD4+ Tfh and Th2 cells sharing antigen specificity serve as an important bridge between humoral and cell-mediated immunity generated after helminth infection." (PMID 34106992, 2021). "This proves that in this model of helminth infection the magnitude of CD4 T cell-mediated immunopathology correlates inversely with the extent of CD4 T cell apoptosis." (PMID 34279684, 2021). "That a majority of 2W1S-specific CD4+ T cells in the lung express GATA3+ is consistent with the expected T cell phenotype during most helminth infections." (PMID 34237106, 2021). "Using various “omic” approaches, the CD4+ T cell receptor (TCR) repertoire was explored after primary helminth infection." (PMID 34106992, 2021). "CD4+ Th2 cells producing IL-4, IL-5, and IL-13 direct cellular immunity in mucosal tissues to maintain barrier integrity after helminth infection." (PMID 34106992, 2021). "Persistent helminth infections appear to induce changes in DNA methylation in CD4+ cells from helminth-infected individuals." (PMID 33692795, 2021). "In the context of helminth infection, IL-5 is known to be produced not only by CD4+ T cells but also type 2 innate lymphoid cells." (PMID 32571840, 2020). "Redundancy between ILC and CD4+ T cells has also been demonstrated in murine infection models, e.g. by ILC2 activity influencing early responses to worm infection but disease ultimately being controlled by CD4+ Th2 cells." (PMID 33343571, 2020). "In another study, IL-9 produced by non-Th2 CD4+ T cell subset during early Nippostrongylus brasiliensis infection in mice provided sufficient host protection against worm infection." (PMID 32243446, 2020). "While there are numerous CD4 T cell subsets, we focused on TH1 and TH2 cells because of their known associations with Mtb and helminth infections, respectively." (PMID 32117277, 2020). "We discovered that CD4+ T cells from patients with MS and concurrent natural helminth infections (HIMS) contained a lower percentage of Th17 cells as well as lineage-specific related genes and dampened DCs activation in a GAS6-dependent manner." (PMID 33347509, 2020). "During helminth infection, ILC2s orchestrate the recruitment of eosinophils and mast cells and, in collaboration with CD4+ T cells, activate M2 macrophage subset development." (PMID 31072011, 2019). "We compared the intestinal helminth infection between individuals with a CD4-positive T cell count < 200 cells/μL and ≥ 200 cells/μL and between individuals with an HIV viral load count < 250 copies/mL and ≥ 250 copies/mL." (PMID 30804703, 2019). "In contrast, helminth infection elicited higher quantities of CD4+ T-cells within the airspace of the lung when compared to naïve mice irrespective of bacterial infection." (PMID 31673002, 2019). "Consistent with previous reports on helminth infections or their products being able to induce the production of Tregs, we discovered that the proportion of CD4+CD25+Foxp3+Tregs in the spleen was increased in SJMHE1‐treated mice." (PMID 31496071, 2019). "ILC2 crosstalk with CD4+ T cells during helminth infection, in addition to their crosstalk with epithelial cells." (PMID 31072011, 2019). "This is similar to the findings in another helminth infection, wherein schistosome infected individuals showed reversal of memory CD4+ T cells after anthelmintic treatment." (PMID 29795573, 2018). "CD4+ memory T cells have been shown to mediate protection against re-infection in experimental helminth infection." (PMID 29795573, 2018). "While CD4+ T cell memory cells are thought to provide protection against re-infection by schistosomes, the prevailing belief is that chronic helminth infection leads to suppression of the CD4 T cell memory compartment." (PMID 29449839, 2017).
helminth infection (continued). "Originally, CD4+T-helper 2 cells immune responses are responsible for the main evolution driving by the helminth infection." (PMID 28151995, 2017). "The immune response to helminth infections is characterized by the induction of CD4+ T-helper 2 (Th2) and down-regulation of CD4+ T-helper 1 (Th1) cells." (PMID 28178325, 2017). "Remarkably, establishment of CAC significantly reduced the IL-4 response of CD4+ T cells after helminth infection which was accompanied by a prolonged survival of the worms." (PMID 28938014, 2017). "Helminth infections are typically characterized by the activation and expansion of CD4+ T helper 2 (Th2) cells, which express the transcription factor GATA-3 and secrete interleukin (IL)-4, IL-5, IL-9, and IL-13, leading to IgG1 and IgE antibody production." (PMID 28791259, 2017). "This study also confirms data from the animal models of helminth infection showing expansion of IL-9 expressing CD4+ T cells." (PMID 26730582, 2016). "One of them concerns the effect of chronic helminth infection on cell specific immune responses in terms of CD4+CD25high Treg cells and the control of other cytokine producing effector (T) cells." (PMID 25120947, 2014). "In contrast, our data suggest that the intrinsic potential of CD4+ T cells to respond to polyclonal stimulation and induce Th1 and Th17 cytokine expression is unaltered in the presence of coincident helminth infection." (PMID 25211342, 2014). "During chronic helminth infections, the increased activation and expansion of CD4+ Th2 cells (including eosinophils, mast cells, basophils, and the antibody isotypes IgG1, IgG4, and IgE) occur." (PMID 24575099, 2014). "In this review, we have focused on recent data concerning the selective priming, differentiation, and functional role of CD4+ T-helper cell subsets in the context of helminth infection." (PMID 25360134, 2014). "Alternatively, it should be noted that helminth infections are also documented to decrease the CD4+ cell population." (PMID 25209883, 2014). "Since both mono - and multifunctional CD4+ Th17 cells have also been implicated as being important in the immune response in active TB, we sought to determine the impact of helminth infection on the CD4+ Th17 responses in TB infected individuals." (PMID 25211342, 2014). "The IL-10 dominated regulatory environment induced in chronic helminth infections is known to modulate the entire repertoire of CD4+ and CD8+ T cell effector functions." (PMID 24699268, 2014). "The modulation of different CD4+ lymphocyte subsets has been observed in many experimental models of helminthosis." (PMID 27335846, 2013). "These seemingly disparate observations highlight the dearth of knowledge that is critical to our understanding of the innate cellular and cytokine mechanisms driving CD4 T cell mediated protective immunity in helminth infections." (PMID 23518620, 2013). "Although this functional plasticity is much better appreciated in studies of CD8 T cells and viral infections, new data and models are emerging for CD4 T cells and innate cells in the context of helminth infections and allergic responses." (PMID 23518620, 2013). "Following helminth infection activated CD200R+ CD4 T cells accumulated substantially and contained IL-4 secreting effector cells." (PMID 22496920, 2012). "We showed previously that the epidermal growth factor family member Amphiregulin is expressed by T cell receptor-activated mouse CD4 T cells, particularly Th2 cells, and helps eliminate helminth infection." (PMID 22720031, 2012). "Helminthic infections themselves promote immune activation leading to immune dysregulation and result in a decrease in CD4+ lymphocytes and an increase in CD8+ cells." (PMID 22860137, 2012). "During experimental helminth infections, CD4+CD25+Treg-mediated suppression of Th2 effector responses confer a permissive state by stifling effective Th2-mediated worm attrition." (PMID 21858239, 2011).
helminth infection (continued). "HIV-1 infected individuals (CD4>250 cells/ul) were screened for helminth infection at ten sites in Kenya." (PMID 20361031, 2010). "One possibility is that this restricted finding is related to immunomodulatory effects of helminth infection that are specific to CD4+ T-cell responses to V. cholerae." (PMID 19333369, 2009). "Three studies also compared changes in HIV-1 RNA or CD4 between treated individuals who cleared their helminth infection at follow-up and individuals who remained infected at follow-up." (PMID 18160978, 2007). "In another study, 21 individuals who cleared their helminth infection had a median increase in CD4 count of 1 cells/μL compared to an increase of 2 cells/μL in 13 individuals with persistent infection (unpublished data provided by authors)." (PMID 18160978, 2007). "Cross–sectional studies of associations between helminth infection and severity of HIV disease, measured by CD4+ T cell count and HIV load, suffer from issues of interpretation that are similar to those for co-prevalence studies." (PMID 17042933, 2006). "Interestingly, CD4 + IL-10+-producing cells from MS patients with helminthic infection showed higher levels of GAS6 expression than Th17 cells, and GAS6 blockade induced an expansion of Th17 effector genes." (PMID 40231720, 2025). "With regards to IL-5, a hallmark of helminth infections, CD4+ T cell responses in pre-patent and Mf-negative mice were comparable which strongly indicates that without developing microfilaremia, responses are dampened or Mf trigger T cell responses." (PMID 39436444, 2024). "In addition, Rorafl/flIL7raCre mice also had a significantly (p < 0.05) reduced frequency of lung GATA3+CD4 Th2 cells after helminth infection, compared with infected Rorafl/fl mice." (PMID 37387671, 2023). "Second, immunoregulation from helminth infections may suppress HIV-1–specific CD4 and CD8 counts, and cytokine production, which may compromise control of HIV-1 replication." (PMID 37561673, 2023). "Notably, IL-13 response by ILC2 was diminished when transferred without OTII T cells, highlighting the interdependency of ILC2 and CD4+ T cell in responding to helminth infections." (PMID 35145516, 2022). "Shared TCRs with common antigen specificities among IL-4-competent CD4+ T cells in both the lung and lung-draining lymph nodes after helminth infection are intriguing when placed in the context of our understanding of Tfh and Th2 cell fate choice during N. brasiliensis infection." (PMID 34106992, 2021). "Single cell transcriptome and chromatin accessibility were subsequently used to identify unique gene sets, regulatory regions, and transcription factor binding sites that discriminate between IFN-gamma+ and IL-4+ CD4+ T cells as well as Th and Tfh subsets responding to helminth infection." (PMID 34106992, 2021). "Th2 cells (CD4+GATA3+) defend against helminth infection and contribute to allergic inflammation." (PMID 34064626, 2021). "The CD4+ T cell response is critical to host protection against helminth infection." (PMID 34106992, 2021). "However, many helminth infections also drive expansion of regulatory T cells (Tregs) that can suppress inflammatory CD4+ T cell subsets." (PMID 34237106, 2021). "The data herein revealed that the responding pool of IL-4+ CD4+ T cells in the lung and lymph nodes after helminth infection represented distinct populations based on their unique gene expression and chromatin accessibility profiles, but shared a common TCR repertoire and overall antigen reactivity." (PMID 34106992, 2021). "Notably, transcription factor NLRP3 (nod-like receptor (NLR) family, pyrin domain containing 3) in CD4+ T cells acts as a key transcription factor in Th2 immune response, which is involved in protective immunity to helminth infection." (PMID 32976511, 2020).